KEAP1 (kelch like ECH associated protein 1)
Diseases named in the same sentence as KEAP1 in open-access papers (continued):
Sharing a sentence is not in itself a finding about the gene and the disease.
colorectal cancer (45 papers, 2012 to 2025). A primary or metastatic malignant neoplasm that affects the colon or rectum. "The research elucidates that LINC00239 achieves inhibition of ferroptosis in colorectal cancer cells by stabilizing NRF2 through its interaction with Kelch-like ECH-associated protein 1 (Keap1)." (PMID 39827195, 2025). "LINC00239 promotes CRC proliferation by interacting with Kelch-like ECH-associated protein 1 (Keap1), leading to instability of the Keap1/Nrf2 complex, and inhibition of Nrf2 ubiquitination to enhance its stability and promote colorectal cancer development." (PMID 40191204, 2025). "In colitis-associated colorectal cancer, IKKβ drives inflammation and tumor progression, while KEAP1 promotes its degradation, exerting an anti-cancer effect." (PMID 40228435, 2025). "The fundamental role of ROS/Kelch-like ECH-associated protein 1 (Keap1)/nuclear factor erythroid 2-related factor 2 (Nrf2)/miRNA34a/b/c axis in regulating the tumor suppressive effects of curcumin has been observed in colorectal cancer." (PMID 39334716, 2024). "This section provides information on how the phytochemicals that regulate Nrf2/KEAP1 are associated with colorectal cancer." (PMID 34067204, 2021). "In particular, Nrf2 gain-of-function mutations have been identified in lung, head and neck, and bladder cancer, while Keap1 loss-of-function mutations have been identified in esophageal, head and neck, liver, gastric, and colorectal cancer." (PMID 34067625, 2021). "Aberrant KEAP1 methylation was also reported in colorectal cancer and head and neck cancer tissues, and was linked to the worst prognoses of these tumors." (PMID 31159323, 2019). "We provide evidence that DLD-1 colorectal cancer grows more rapidly in mice characterized by higher energy expenditures, which is associated with differences in ROS levels, the antioxidant barrier, and Keap1 expression." (PMID 39409042, 2024). "Apoptosis was associated with the RKIP/KEAP1 expression levels in colorectal cancer tissues, providing another mechanism by which diminution of RKIP levels may result in resistance to therapy." (PMID 24098947, 2013). "This pathway exhibits context-dependent duality: pro-death in colorectal cancer via Auriculasin-enhanced KEAP1/AIFM1 signaling versus pro-survival upon KEAP1/AIFM1 inhibition." (PMID 40741332, 2025). "In colorectal cancer, NRF2 overexpression has been linked to distant metastasis through the induction of HO-1, while elevated KEAP1 levels in tumor tissue have been associated with lymphovascular invasion." (PMID 41470226, 2025). "Epigenetic modifications, such as enrichment of H3K4Me3 and H3K27Ac on the promoter of KEAP1, was known to regulate KEAP1 expression in colorectal cancer." (PMID 36419136, 2022). "In this review, we have demonstrated the significance of the Nrf2/KEAP1 signaling pathway and the anticancer effect of phytochemicals targeting the Nrf2/KEAP1 axis in colorectal cancer cells as well as animal models." (PMID 34067204, 2021). "In this review, we summarize the role of oxidative stress and the Nrf2/KEAP1 signaling pathway in colorectal cancer, and the possible utility of phytochemicals with respect to the regulation of the Nrf2/KEAP1 axis in colorectal cancer." (PMID 34067204, 2021). "The activation of NRF2 in colorectal cancer has been shown to happen through at least two different mechanisms: hypermethylation of the KEAP1 promoter and deubiquitination of NRF2." (PMID 32992842, 2020). "Promoter hypermethylation of Keap1 has been observed in several types of cancers, such as lung, breast and colorectal cancers." (PMID 30811526, 2019).
colorectal cancer (continued). "Aberrant KEAP1 methylation was also reported in 53% of colorectal cancer, head and neck cancer tissues (29.3%) and prostate cancer cells as the main mechanism of epigenetic silencing of KEAP1 expression with clinical prognostic significance." (PMID 31159323, 2019). "Aberrant NRF2 activation due to KEAP1 alterations is also reported as one of the molecular mechanisms of chemoresistance of gallbladder cancer under 5-FU-based regimen and of colorectal cancer under demethylase and methyltransferase treatments." (PMID 29643973, 2018). "Aberrant KEAP1 methylation was also reported in 53% of colorectal cancer and head and neck cancer tissues (29.3%) and was also linked to the worse prognosis of these tumors." (PMID 29643973, 2018). "The mRNA levels of Hmox1, Nrf2, Keap1, and Bach1 in the tumor and normal tissues of 84 subjects with colorectal cancer (CRC) were determined by real-time polymerase chain reaction." (PMID 27999449, 2016). "This leads to a reduction in Keap1 expression, and in the case of prostate and colorectal cancer cells, an increase in the expression of Nrf2-target genes." (PMID 24681086, 2014). "In addition, in colorectal cancer cells, curcumin inhibited colorectal cancer metastasis by activation of the ROS/KEAP1/NRF2/miR-34a/b/c pathway." (PMID 40437595, 2025). "Moreover, it has been observed that LINC00239 promotes the proliferation of colorectal cancer cells by interacting with Keap1, leading to instability of the Keap1/Nrf2 complex." (PMID 39210921, 2024). "Curcumin can activate ROS/KEAP1/NRF2/miR-34a/b/c cascade to inhibit colorectal cancer metastasis." (PMID 39311951, 2024). "LINC00239 inhibits ferroptosis in colorectal cancer by binding to Keap1 to stabilize Nrf2." (PMID 36038548, 2022). "However, validation through clinical research and studies on phytochemicals that control colorectal cancer through the Nrf2/KEAP1 signaling pathway are still insufficient and further research is required." (PMID 34067204, 2021). "List of phytochemicals targeting Nrf2/KEAP1 for colorectal cancer." (PMID 34067204, 2021). "In colorectal cancer, genetic alterations of KEAP1 or NFE2L2 are rare (less than 2%)." (PMID 32992842, 2020). "Current studies have shown that piperine can inhibit colorectal cancer by regulating STAT3/Snail-mediated epithelial–mesenchymal transition (EMT), Nrf-2/Keap-1, and Wnt/β-catenin pathways, indicating that piperine may affect colorectal cancer through multiple signaling pathways." (PMID 38972051, 2025). "In addition, Ginnalin A, a polyphenolic compound isolated from red maple (Acer rubrum), inhibits cell viability and colony formation in colorectal cancer, inducing cell cycle arrest by activating the Nrf2/HO-1 pathway through the up-regulation of p62 and the inhibition of Keap1." (PMID 34067625, 2021). "We used colorectal cancer (CRC) cell lines and surgical specimens to investigate the methylation status of the KEAP1 promoter region as well as expression of Nrf2 and its downstream antioxidative stress genes, NQO-1 and AKR1C1." (PMID 22325485, 2012). "However, the status of Keap1-Nrf2 system in human colorectal cancer (CRC) has not been elucidated." (PMID 22325485, 2012).
Obesity (45 papers, 2013 to 2025). Accumulation of substantial excess body fat. "Genetically modified mouse models such as Nrf2 KO and Keap1 KD have been frequently used in the setting of high-fat diet-induced obesity because of the strong association between obesity and insulin resistance." (PMID 32971975, 2020). "Nrf-2 and its partner Kelch-Like ECH-Associated Protein 1 (Keap-1) have been linked to the oxidative stress response in tissues such as adipocytes, as a consequence of obesity, and in peripheral blood mononuclear cells, as a consequence of smoking." (PMID 25705690, 2015). "As discussed, obesity fuels oxidative stress by increasing oxidant species; however, it also represses antioxidant defenses, particularly via the Keap1-Nrf2-ARE (Kelch-like ECH-associated protein 1–nuclear factor erythroid 2-related factor 2–antioxidant response element) signaling pathway." (PMID 40002337, 2025). "In line with this evidence, the reduction in the nuclear activities of Nrf2 in the livers of HFD-fed rats was associated with a concomitant increment in the mRNA of Keap1, which could be due to obesity-induced IR and hyperglycemia." (PMID 40869259, 2025). "Further research is needed to address obesity‐associated interactions between Nrf2 and Keap1." (PMID 39230054, 2024). "However, KEAP1-KD in C57Bl/6J, Lepob/ob mice, an obesity animal model with leptin deficiency, even though it showed less lipid accumulation, smaller adipocytes, decreased food intake, and reduced lipogenic gene expression." (PMID 37047024, 2023). "The question emerges whether the improved obesity in Keap1-KD mice is the effect of Nrf2 activation, or an indirect result of decreased food intake caused by Keap1 gene manipulation." (PMID 36290791, 2022). "In this study, we showed that PMQ could resist cardiac remodeling associated with obesity, which might be mediated by improving the metabolism disorders and enhancing the endogenous antioxidant system of the sestrins/Keap1/Nrf2 signaling pathway." (PMID 32090078, 2020). "Similarly, the Keap1-hypo allele (Nrf2 activation) mice were partially protected from obesity, had lower fasting glucose and insulin levels, and developed less liver steatosis." (PMID 32443555, 2020). "In fact, microbe-induced ROS generation and activation of Keap1/Nrf2/ ARE signaling may contribute to our understanding on the mechanisms involved in the genesis of obesity and diabetes, comorbidities associated with increased cardiovascular risk." (PMID 31031630, 2019). "In this study the authors also made use of a genetic model of obesity, the Lepob/ob mouse that is homozygous for a mutation in the leptin gene and become obese, hyperphagic, hyperglycemic and glucose intolerant and produced the Keap1 flox/flox:Lepob/ob mouse." (PMID 23363332, 2013). "Besides the elucidation of the exact mechanisms that underlie the effect of Nrf2 on obesity and metabolism in general, it is important to consider which options are already available for clinical manipulation of the Keap1/Nrf2 pathway." (PMID 23363332, 2013). "Molecular investigation showed that CXCL1 triggered KEAP1 m6A demethylation via FTO (fat mass and obesity-associated protein) up-regulation, subsequently reducing NRF2 expression to exacerbate ROS burst and mitochondrial fission." (PMID 41255573, 2025). "Our results align with earlier studies showing that PTL activates the Nrf2/Keap1 axis through elevating Nrf2 and suppressing Keap1 protein contents in adipocytes in an obesity-induced inflammatory response model, and in an adipocyte differentiation model." (PMID 39327568, 2024). "Although Nrf2 is generally required for HFD-induced obesity, as mentioned, constitutive Nrf2 activation by Keap1 KD also inhibited HFD-induced obesity by decreasing PPARγ and C/EBPα." (PMID 37892226, 2023).
Obesity (continued). "Another study investigated the effect on the NRF2 pathway of HFD-induced (39.7 kcal% fat) obesity among Nfe2l2-KO, WT, and Keap1-KD mice and concluded that the genetic alteration of Nfe2l2 does not prevent diet-induced obesity in mice." (PMID 35204118, 2022). "Obesity‐enhanced oxidative stress was associated with lower GPx activity and higher TOS and Keap1 AA genotype correlated with lower GPx activity." (PMID 34861061, 2022). "This study evaluated the therapeutic effects of Heterotrigona itama BB from Malaysia on obesity-induced hepatic lipid metabolism disorder via the regulation of the Keap1/Nrf2 pathway." (PMID 36358563, 2022). "Our study suggests the role of reduced antioxidant system and Keap1 variants in the pathogenesis of T2DM and its complications of neuropathy and retinopathy and also obesity in enhanced oxidative stress." (PMID 34861061, 2022). "Either by deleting Nrf2 or activating Nrf2, e.g., via Keap1 deletion, a number of in vivo mouse studies have addressed the role of Nrf2 in diet-induced obesity." (PMID 34298930, 2021). "Induction of Nrf2 in young adult Keap1-KO mice slowed their weight gain trajectory and conferred protection against diet-induced obesity while maintaining diurnal metabolic flexibility in their use of fuels for energy needs." (PMID 33298924, 2020). "Activation of the Nrf2 pathway in Keap1 hypomorphic mice can protect mice on HFD or genetically obese db/db mice from the development of obesity and T2D3." (PMID 33298924, 2020). "Lastly, parthenolide and epigallocatechin 3-gallate can inhibit obesity and obesity-induced inflammatory responses via Nrf2/Keap1 signaling under high-fat diet conditions." (PMID 32971975, 2020). "We discovered that obesity increased the expression of Keap1 and decreased levels of Nrf2 as well as the activation of other antioxidant enzymes, indicating that obesity-induced oxidative stress improved by stimulation of the Nrf2 antioxidant pathway." (PMID 31591291, 2019). "The expression of Keap1 was significantly increased by obesity and decreased via treatment of 20 mg/kg SFN in obese mice (p < 0.05)." (PMID 31591291, 2019). "Previous studies using mouse models have shown that activation of the Keap1/Nrf2 pathway, at least partially protected mice from diet-induced obesity and amelioration of hepatic steatosis." (PMID 27973423, 2016). "Experiments using Nrf2 KO or Keap1-KD mice, which have a constitutive altered Nrf2 pathway, showed various effects on obesity." (PMID 24194976, 2013). "Another approach to study the role of Nrf2 in HFD-induced obesity and T2D is the use of pharmacological substances that activate the Keap1/Nrf2 pathway by interacting with the reactive cysteines in Keap1 and accelerate nuclear accumulation of Nrf2." (PMID 23363332, 2013). "At present, the Keap1/Nrf2 system appears to be an attractive target for obesity and metabolic syndrome treatment and prevention." (PMID 23363332, 2013). "In the same study, a short-term (5 weeks) HFD-induced obesity experiment was performed on wild-type and Keap1 flox/flox mice where it was shown that Nrf2 gain of function protected mice from obesity and led to less WAT accumulation." (PMID 23363332, 2013). "Several studies have examined how Nrf2 could affect obesity or IR using systemic Nrf2 or Keap1 knockdown (KD) mice (i.e., constitutive Nrf2 activation model)." (PMID 37892226, 2023). "In addition, parthenolide and epigallocatechin 3-gallate showed the capacity to inhibit obesity and obesity-induced inflammatory responses via NRF2/KEAP1 signaling under HFD conditions." (PMID 35204118, 2022). "Furthermore, Pun also displayed that it can suppress the obesity and obesity-induced inflammatory responses through the Nrf2/Keap1 signaling pathway." (PMID 35028666, 2022). "Our findings suggest that pharmacologic inhibition of Keap1 may offer such approach, particularly for conditions such as obesity-induced metabolic syndrome." (PMID 33103077, 2020).
Obesity (continued). "In another study, Zhang Y and colleagues investigated the effect of the Nrf2 pathway on high-fat diet-induced (39.7 kcal% fat) obesity among Nrf2-KO, WT, and Keap1-knockdown mice, which concluded that the genetic alteration of Nrf2 does not prevent diet-induced obesity in mice." (PMID 32971975, 2020). "Interestingly, knockout mice for the Keap-1 protein exhibit similar features, including suppression of high-fat diet-induced obesity and decreased deposition of lipids and cholesterol in the liver." (PMID 31031630, 2019). "Therefore, we also examined how Keap1 expression is affected by HFD /obesity in female brain." (PMID 39230054, 2024). "Before the development of Keap1-disrupted mouse models, investigations on the roles of NRF2 in obesity and diabetes focused on exacerbation of disease in Nrf2 knockout mice and protection by small molecule inducers of NRF2 signaling." (PMID 37686150, 2023). "The oleane triterpenoid CDDO-Im, which is known to target NRF2 signaling through binding to specific cysteine residues in KEAP1, is partially preventive against high fat diet (HFD)-induced obesity." (PMID 37686150, 2023). "In summary, parthenolide inhibits obesity and obesity-related inflammatory responses through the activation of the NRF2/Keap1 signaling pathway." (PMID 35955599, 2022). "Obesity and DEHP significantly increased the levels of Keap1 protein by 130%, 117%, 135%, 129%, and 167% in the DEHP, DIO, DIO + DEHP low, DIO + DEHP middle, and DIO + DEHP high groups, respectively, compared to the controls (P < 0.05)." (PMID 29887939, 2018). "Through activating the TDP43/Raptor/p62/Keap1/NRF2 axis, the reduction of Chchd10 in response to energy surplus awakens the adaptive response, which potentiates adipogenesis and GSTA4‐mediated 4‐HNE clearance to combat obesity." (PMID 39985288, 2025). "On the other hand, high fat diet-induced obesity and lipid accumulation in white adipose tissue was decreased in C57Bl/6J, KEAP1-KD mice without an Lepob/ob background." (PMID 37047024, 2023). "Neither Nrf2 nor Keap1 was affected by maternal obesity or grape juice intake, and antioxidant genes Ogg1, Ogg2, Sod1 or Sod2 were not affected either." (PMID 32731460, 2020). "Although the mechanisms by which β-cryptoxanthin prevents obesity have not been entirely clarified, it was suggested that β-cryptoxanthin might induce PPAR-α, antagonize PPAR-γ, and upregulate Keap1/Nrf2 pathway." (PMID 33799771, 2021).